BCL2 (BCL2 apoptosis regulator)
Diseases named in the same sentence as BCL2 in open-access papers (continued):
Sharing a sentence is not in itself a finding about the gene and the disease.
osteosarcoma (continued). "RBM10 overexpression induced osteosarcoma cell apoptosis via the inhibition of Bcl-2, the activation of caspase-3, and the transcription and production of TNF-α." (PMID 34804951, 2021). "In our previous studies, several target genes were found to participate in the regulation of osteosarcoma, such as BCL-2, PTEN, BCL-xL, and KRAS." (PMID 32152265, 2020). "According to recent reports, upregulation of Bax/Bcl-2 ratio can inhibit proliferation in human osteosarcoma cells." (PMID 32922188, 2020). "CT induced S-phase cell cycle arrest, apoptosis, and mitochondrial fragmentation in osteosarcoma cells with increased Bax, Bad, and Bak; decreased Bcl-2; and the activation of caspase-3, caspase-8, and caspase-9 expressions." (PMID 32265690, 2020). "For the first time, we have identified that Lnc-MAP6-1:3 potentially influence the malignant behavior of osteosarcoma via Bax/Bcl-2 and Wnt/β-catenin signaling pathways." (PMID 32922188, 2020). "Over-expression of miR-181a leads to increased viability of osteosarcoma cells and induced cell proliferation by augmenting BCL2, MMP9; and apoptosis was inhibited by down-regulation of p21 and TIMP3 expression." (PMID 32932883, 2020). "Apatinib can inhibit tumor cell growth by blocking the VEGFR2/STAT3/Bcl-2 or Akt/GSK3β/angiogenin signaling pathways, suppressing tumor angiogenesis in osteosarcoma and anaplastic thyroid cancer, respectively." (PMID 32509141, 2020). "Consistently, the up-regulation of BAX and suppression of Bcl-2 by sclareol has been previously reported in osteosarcoma cells." (PMID 32922496, 2020). "BCL-2 protein can be targeted by several microRNAs such as miR-143, whereby an overexpression of miR-143 in osteosarcoma promotes apoptosis by downregulating BCL-2." (PMID 31652776, 2019). "In contrast, the inhibition of ERK1/2 MAPK in osteosarcoma cells prevented the paradoxical effect of doxorubicin-induced expression of BCL-2 and BCL-XL, thereby improving the sensitivity of doxorubicin-killing in these cells." (PMID 31652776, 2019). "Our results demonstrate that LicA induced osteosarcoma cell mitochondrial dysfunction through a decrease in the expression of Bcl-2 and Mcl-1 and an increase in the expression of Bax." (PMID 31739642, 2019). "It has been reported that NC inhibited cell proliferation and induced apoptosis via the upregulation of cleaved caspase-3, cleaved caspase-9, and Bax and the downregulation of Bcl-2 in osteosarcoma cells." (PMID 30847386, 2019). "According to the western blot results, bcl-2, cox-2, and fak were down-regulated whereas caspase-3, caspase-9, p-53, nf-kb, and bax were upregulated in osteosarcoma cells in response to CC/Se-HAp nanoparticles treatment as compared to control." (PMID 31263675, 2019). "Consistently, it has been proved that adenoviral vector-mediated IL-24 expression suppresses the growth of MG-63 osteosarcoma cells through down-regulating Bcl-2 expression, and up-regulating Bax and Caspase-3 expressions." (PMID 29899165, 2018). "Previous study proved that DMY suppressed caspase activation but elevated Bcl-2 expression to exhibit a powerful anti-apoptosis effect on osteosarcoma cells." (PMID 30200365, 2018). "Polydatin can inhibit cell proliferation via attenuating the β-catenin signaling and promotes cell apoptosis via up-regulation the ratio of Bax/Bcl-2 in osteosarcoma." (PMID 29513792, 2018). "Survivin and its downstream target Bcl-2 were significantly suppressed in osteosarcoma cells after a short time of treatment with low concentrations of panobinostat." (PMID 30250645, 2018).
osteosarcoma (continued). "A recent study suggested that Apatinib promotes autophagy and induces apoptosis through VEGFR2/STAT3/BCL-2 signaling in osteosarcoma." (PMID 29490645, 2018). "Apatinib repressed the expression of STAT3 and BCL-2 and suppressed the growth of osteosarcoma in vivo." (PMID 28837148, 2017). "Bufalin inhibited cell growth via the down-regulation of Bcl-2/Bax and the triggering of the mitochondrial pathway in human osteosarcoma MG-63 cells." (PMID 28287444, 2017). "In the current study, Tan IIA decreased Bcl-2 expression and increased caspase 3 expression, accompanied by an elevated Bax, Bad and Bak expression in osteosarcoma 143B cells and osteosarcoma 143B xenograft mice." (PMID 28106052, 2017). "Together, these results suggest that reduced WWOX expression in osteosarcoma cells inhibited apoptosis, promoted invasion, upregulated bcl-2, OPN, RUNX2, and VEGF expression, and increased microvessel density (MVD)." (PMID 28977834, 2017). "The finding was validated by the overexpression of BCL-2 in osteosarcoma cells, which inhibited Apatinib-induced autophagy." (PMID 28837148, 2017). "On the contrary, upregulation of Let-7d reduced cell sensitivity to apoptosis and induced drug resistance in 3AB-OS cells, in combination with decreased caspase-3 and increased Bcl-2 in osteosarcoma." (PMID 28978183, 2017). "Anticancer activity of KP46 against osteosarcoma cell models was evaluated as single agent and in combination approaches with chemotherapeutics and Bcl-2 inhibitors using MTT assay." (PMID 28403890, 2017). "Previously, we reported that miR-143 expression was decreased in osteosarcoma tissues, and miR-143 decrease was responsible for the increased anti-apoptotic Bcl-2 expression in osteosarcoma." (PMID 28977896, 2017). "Our results suggest that constitutive TERT expression antagonizes cisplatin-induced apoptosis via regulation Bcl-2, Bcl-xl, Bax and caspase-3 in osteosarcoma cells." (PMID 28765565, 2017). "PVT1 consequently inhibits the apoptosis of osteosarcoma cells via miR-195/BCL2, induces cell-cycle arrest in osteosarcoma cells via miR-195/CCND1, and promotes the migration and invasion of osteosarcoma cells via miR-195/FASN." (PMID 27813492, 2016). "Evodiamine effectively inhibited proliferation and induced apoptosis of osteosarcoma cells in a dose-dependent manner via downregulation of Bcl-2, caspase-3 and survivin protein expression levels and upregulation of Bax protein expression levels." (PMID 25621054, 2015). "Western blotting demonstrated that evodiamine downregulated the expression of Bcl-2, caspase-3 and survivin, and upregulated the expression of Bax in human osteosarcoma cells." (PMID 25621054, 2015). "Luteolin can inhibit osteosarcoma cell proliferation and induce apoptosis effectively in a dose dependent manner through down-regulating the expression of BCL-2, Caspase-3 and Survivin proteins levels and up-regulating the expression of BAX protein level." (PMID 25901161, 2015). "By studying the effects of HYG on hTERT and Bcl-2 protein in osteosarcoma cells, this experiment provides a theoretical basis for clinical application of HYG in treatment of osteosarcoma." (PMID 25371846, 2014). "The first study demonstrated that an increased bax/bcl-2 protein expression ratio was indicative of osteosarcoma patients with an unfavorable prognosis." (PMID 24137369, 2013).
osteosarcoma (continued). "Of the 49 osteosarcomas studied, 21 cases (43%) were classified as bcl-2-positive, and the immunostaining in the majority of these tumors was heterogenous and contained positive areas." (PMID 24137369, 2013). "A previous study in human osteosarcoma revealed marked bcl-2 expression in 46% and moderate expression in 35% of all cases." (PMID 24137369, 2013). "The expression of bcl-2 was examined immunohistochemically in 49 patients with high-grade osteosarcoma and the results were correlated with localization, histological response to chemotherapy, survival and the occurrence of metastases." (PMID 24137369, 2013). "In the centrally-located osteosarcomas (spine or ileum), 5/6 (83%) were positive for bcl-2, whereas only 16/43 (37%) of the peripheral osteosarcomas of the long bones were positive." (PMID 24137369, 2013). "Knockdown of IGF1R in osteosarcoma cell lines induces apoptosis, inhibits cell proliferation and enhances chemo- and radio-sensitivities by decreasing Bcl-2 expression and increasing Caspase-3 and Bax expression." (PMID 24391788, 2013). "Crude acetone extracts of R. verniciflua Stokes, which is rich in fustin and fisetin, and butein-triggered osteosarcoma cells undergo apoptosis via the activation of Bax and the down-regulation of Bcl-2 expression." (PMID 22245810, 2012). "ERK1/2 inhibition prevented doxorubicin-induced upregulation of Bcl-2 and Bcl-xL, thereby increasing doxorubicin sensitivity in osteosarcoma cells." (PMID 22577336, 2012). "Doxorubicin paradoxically upregulated antiapoptotic proteins such as Bcl-2 and Bcl-xL by osteosarcoma cells in vitro." (PMID 22577336, 2012). "It has been shown that p16INK4a-deficiency increases apoptosis in osteosarcoma U2OS and mouse embryonic fibroblast (MEF) cells exposed to ultraviolet (UV) light, because of down-regulation of the anti-apoptotic protein Bcl-2." (PMID 21359218, 2011). "Celecoxib triggered also apoptosis in osteosarcoma cells (MG-63) through down-regulation of Bcl-2, survivin and PI3K (phosphoinositide 3-kinase) pathway." (PMID 20339581, 2010). "Therefore, the combination enhanced the level of apoptosis in osteosarcoma cells and down-regulating the expression of Bcl-2/Bax by HMGCR-miR-27a-3p-BCYRN1 axis." (PMID 40764575, 2025). "Furthermore, the knockdown of circUBAP2 expression inhibited the expression of Bcl-2 and significantly promotes apoptosis in osteosarcoma cells (MG63 and U2OS)." (PMID 40283955, 2025). "Furthermore, NF-κB activation following radiation therapy induces the expression of anti-apoptotic proteins like Bcl-2 and Bcl-xL, which protect osteosarcoma cells from radiation-induced apoptosis." (PMID 39949765, 2025). "Osteosarcoma cells frequently become resistance to chemotherapy by upregulating NF-κB-mediated survival pathways, including the expression of anti-apoptotic proteins like Bcl-2 and Bcl-xL." (PMID 39949765, 2025). "Chemotherapeutic agents, including methotrexate, cisplatin and doxorubicin, are widely employed in osteosarcoma treatment, but their anticancer efficacy may be hindered by anti‐apoptotic proteins such as BCL‐2, MCL‐1, c‐FLIP and XIAP." (PMID 40889216, 2025). "This consistent pattern emphasizes the significance of targeting Bcl2 as a therapeutic strategy against cancer, including osteosarcoma, and suggests that A. lanata may have potential as a natural agent for Bcl2-targeted therapy in this setting." (PMID 38738026, 2024). "Moreover, TGT triggers cell apoptosis in osteosarcoma cells by controlling the levels of Bax and Bcl-2." (PMID 38297292, 2024). "We demonstrated that osteosarcoma cell lines could be killed through inhibition of MCL-1 combined with BCL-2 or BCL-xL antagonism." (PMID 39497108, 2024). "According to the study, this dysregulation was correlated with the prognosis of osteosarcoma patients, with those exhibiting high levels of Bcl‐2 expression had a poorer prognosis and stronger tumor metastasis compared to patients with low levels of Bcl‐2 expression." (PMID 38800967, 2024).
osteosarcoma (continued). "In this study we showed that inhibition of MCL-1 (with S63845) combined with inhibition of BCL-2 (with ABT-199) or BCL-xL (with A-1331852) consistently reduced the viability of osteosarcoma cells in vitro when drugs were applied at low micromolar concentrations." (PMID 39497108, 2024). "Indeed, Bcl-xL and Bcl-2 are promising targets in the treatment of chondrosarcomas and osteosarcomas." (PMID 37719019, 2023). "In addition, we discovered that U2OS and 143B osteosarcoma cells exposed to PIP combined with DOX exhibited a remarkable lower expression of apoptosis-resistant proteins Bcl-2." (PMID 36895009, 2023). "According to molecular docking results, angelicin could bind freely to the hub targets, and the hub targets BAX, BRIC2, BCL2, and Casp9 may be effective targets by which angelicin affects osteosarcoma cells." (PMID 37301545, 2023). "In addition, the binding of CypD and Bcl-2 enhances the limiting effect of Bcl-2 on cytochrome C (Cyto C) release and improves the antiapoptotic effect of various tumor cell lines (human osteosarcoma cell line Saos2 and human acute leukemia cell line HL60)." (PMID 35860554, 2022). "We suspect that the pro-apoptotic effects of miR-342-5p are linked to Bcl-xL inhibition rather than to Bcl-2 inhibition in osteosarcoma cells." (PMID 35337159, 2022). "In summary, the inhibition of the expression of Bcl-xL and Bcl-2 may be responsible for the pro-apoptotic effect of miR-342-5p on osteosarcoma cells, and that of Bcl-xL may be involved in the pro-apoptotic effect of miR-491-5p." (PMID 35337159, 2022). "It was reported that downregulation of pro-apoptotic molecules Bax and FasL and upregulation of anti-apoptotic molecule Bcl-2 could effectively inhibit caspase-dependent apoptosis in human osteosarcoma cells." (PMID 35401542, 2022). "Immunohistochemistry was used to analyse the expression of BCL-2 in osteosarcoma." (PMID 34565443, 2021). "Besides, DT-I increased the expression of PARP and caspase-3, decreased the expression of Bcl-2, and induced apoptosis of osteosarcoma cells through mitochondrial pathway." (PMID 32265690, 2020). "One review reported that Bcl-2 might be a new molecule in osteosarcoma targeted therapy, and Bcl-2 was markedly downregulated in cisplatin-treated Barkor-transfected Saos-2 cells in a dose-dependent manner." (PMID 32713851, 2020). "Furthermore, we observed that p21, caspase-3 and cleaved caspase-3 are increased while the expression of cycinD1 and bcl-2 are decreased after REG γ depletion in osteosarcoma cells." (PMID 32328351, 2020). "miR-326 suppresses the antiapoptotic gene BCL-2 in osteosarcoma and acts as a tumor suppressor." (PMID 32318335, 2020). "For example, OST could inhibit cell proliferation and induce apoptosis by downregulating caspase-3 expression and upregulating the Bax/Bcl-2 ratio in human osteosarcoma MG-63 cells." (PMID 31354479, 2019). "Additionally, we noted an increased Bax/Bcl-2 ratio in all osteosarcomas cell lines, however significant results were noted only for Saos-2 and MG-63 cell line." (PMID 31752084, 2019). "Furthermore, AuNPs rods and AuNPs stars caused increased expression of Bax and decreased expression of Bcl-2 protein in osteosarcoma cells." (PMID 30747353, 2019). "Apatinib inhibited osteosarcoma growth in vitro by inducing autophagy and apoptosis of osteosarcoma cells via directly inhibiting expression of the antiapoptotic protein Bcl-2 and inactivating signal transducer and activator of transcription 3 (STAT3), which is mediated by VEGFR248." (PMID 30816108, 2019).
osteosarcoma (continued). "SNHG20 is up-regulated in osteosarcoma tissues and cells and knockdown of SNHG20 up-regulates the expression of apoptosis-related protein Bax, decreases the expression of Bcl-2, inhibits the activity of caspase-3 and caspase-9, and promotes the apoptosis of osteosarcoma cells." (PMID 30744670, 2019). "The expression of Survivin and its downstream target Bcl-2 was analysed in osteosarcoma cells." (PMID 30250645, 2018). "In addition, polydatin promotes apoptosis through upregulating the ratio of Bax/Bcl-2 and inhibiting proliferation by attenuating the beta-catenin signaling in human osteosarcoma cells." (PMID 29513792, 2018). "To identify the underlying molecular mechanisms, we used western blotting to analyze the levels of Bcl-2, Bax, p-Akt, cleaved caspase-3, and cleaved caspase-9, which are very important in the regulation of apoptosis in osteosarcoma cells following cisplatin treatment." (PMID 29731768, 2018). "Increased apoptosis of osteosarcoma cells by co-treatment of olaparib and doxorubicin was associated with increased expression of cleaved PARP1, cleaved caspase 3, and BAX, and decreased expression of BCL2." (PMID 29784019, 2018). "In addition, miR-21 reduced the anti-tumor effect of cisplatin by regulating Bcl-2 expression in osteosarcoma cells." (PMID 29113367, 2017). "Bcl-2 has anti-apoptotic effects in a variety of tumors, including osteosarcoma." (PMID 28977834, 2017). "As circUBAP2 was found to bind miR-143, we next examined that whether circUBAP2 could function as the sponge of miR-143 and inhibit miR-143 expression, thus upregulating Bcl-2 expression in osteosarcoma." (PMID 28977896, 2017). "As miR‐15b and its targeted genes, including Wee1 and Bcl‐2, hold great potential for the treatment of chemoresistance, this research provides strong evidence for future development of miR‐based therapeutics strategies directed at treating osteosarcoma." (PMID 28145098, 2017). "In addition to miR-21, miR Let-7d also reduced cell sensitivity to DOX, CDDP, etoposide and paclitaxel, consistent with increased expression of Bcl-2 in osteosarcoma." (PMID 28978183, 2017). "Thus, we conclude that circUBAP2 is the sponge of miR-143 and then upregulates anti-apoptotic Bcl-2 expression in osteosarcoma." (PMID 28977896, 2017). "Ferulic acid could significantly descend osteosarcoma cell viability through the promoting apoptosis pathway in which FA activates both caspase-3 and Bax and inactivates Bcl-2." (PMID 28367185, 2017). "In this study, we found that circUBAP2 expression is significantly upregulated in osteosarcoma, and circUBAP2 could promote osteosarcoma growth by enhancing anti-apoptotic Bcl-2 expression." (PMID 28977896, 2017). "As Bcl-2 is an important anti-apoptotic molecule well-accepted to protect osteosarcoma cells from apoptosis, we conclude that circUBAP2 may inhibit osteosarcoma cell apoptosis by upregulating Bcl-2 expression." (PMID 28977896, 2017). "In addition, WWOX inhibited the expression of bcl-2, OPN, RUNX2, and VEGF in osteosarcoma cells, while bcl-2 increased VEGF expression and RUNX2 increased VEGF and OPN expression in MG-63 cells." (PMID 28977834, 2017). "Our studies demonstrated that luteolin inhibited MG-63 osteosarcoma cell proliferation and induced apoptosis effectively in a dose dependent manner through down-regulating the expression of BCL-2, Caspase-3 and Survivin proteins levels and up-regulating the expression of BAX protein." (PMID 25901161, 2015). "BCL2L2 amplification in osteosarcoma has not been reported previously, but 25% of osteosarcomas express the related protein Bcl-2, which has been linked with decreased long-term survival." (PMID 25126591, 2014). "In the present study, we demonstrate that products of lipid peroxidation, HNE, could induce cell death in MG63 human osteosarcoma cells by altering Bcl-2/Bax ratio and activating caspase-3 cascades." (PMID 24711740, 2014).